IL18 (interleukin 18)
Diseases named in the same sentence as IL18 in open-access papers (continued):
Sharing a sentence is not in itself a finding about the gene and the disease.
periodontitis (continued). "We found that only IL-18 was elevated in the serum and GCFs of periodontitis patients, and effective periodontal therapy dampened IL-18 production in GCFs, indicating the signature role of periodontium-resident IL-18 in the pathogenesis of periodontitis." (PMID 33679805, 2021). "DC may promote alveolar bone resorption via IL-1β induction in periodontitis patients, but suppress resorption via IL-18 and IL-10 induction in some circumstances." (PMID 34830316, 2021). "Animal models in rhesus monkeys have shown a downregulation of IL-18 mRNA in early periodontitis, suggesting that lower expression of the cytokine could be responsible for an impaired Th2 inflammatory response in periodontal disease." (PMID 34685372, 2021). "However, we did not characterize the pathways that are potentially involved and link IL-18 and MMPs/TIMPs in P. gingivalis-induced periodontitis due to the limited sample size." (PMID 33679805, 2021). "Notably, salivary IL-18 levels rose up to > 5-fold in patients with chronic periodontitis compared with healthy individuals." (PMID 32053656, 2020). "In addition to the potential role of IL-17A and IL-18 in the local involvement of periodontitis, a systemic role of these cytokines and interactions with DM has also been recognized." (PMID 32053656, 2020). "Therefore, this study was aimed to investigate the local and systemic role of IL-17A and IL-18 by measuring salivary and serum levels in subjects with type 2 DM and periodontitis." (PMID 32053656, 2020). "The present study aimed to investigate the salivary and serum levels of inflammatory cytokines IL-17A and IL-18 in subjects with different glycemic and periodontal status in order to clarify the interrelationship among these cytokines, type 2 DM, and periodontitis." (PMID 32053656, 2020). "The IL18-137G/C genotype was associated with the risk of chronic periodontitis in nonsmokers (Pc = 0.03; OR = 1.99; overdominant inherence model)." (PMID 31065235, 2019). "Also, the cells exposed to H2S secreted higher levels of IL-1β and IL-18 in the periodontitis group compared to the healthy group (p= 0.03 and p= 0.04, respectively)." (PMID 31164964, 2019). "The results demonstrated that IL-18 concentration in the crevicular gingival fluid was low in the group with healthy periodontium and progressively increased in groups from gingivitis, to aggressive periodontitis, and finally chronic periodontitis." (PMID 30467497, 2018). "Because the periodontal status of the donors is unknown, we can only speculate that the cells with higher IL‐1β and IL‐18 responses are from donors more prone to develop periodontal disease." (PMID 29744188, 2017). "Some researchers believe that reduced values of IL-12 paired with the increased values of IL-18 might shift the response of T-lymphocyte toward T-helper 2 phenotype and have reported this event in periodontitis." (PMID 29299075, 2017). "Several studies have shown that also IL-18 can influence the pathogenesis of chronic periodontitis." (PMID 27403039, 2016). "Although the assessment of IL-18 in gingival tissue in our study is limited by the number of cases examined, it appears that the expression of IL-18 in the gingiva of patients with periodontitis may be the result of chronic inflammation and the action of other pro-inflammatory factors." (PMID 36289627, 2022). "It cannot be excluded that, in periodontitis patients, IL-18 may have some beneficial effects." (PMID 36289627, 2022). "IL-18 may therefore directly or indirectly contribute to periodontal disease by promoting the migration of inflammatory cells, which are known to induce periodontitis, into the periodontium." (PMID 33679805, 2021). "IL-18 has also been shown to promote neutrophil recruitment and induce cytokine/chemokine and MMPs expression, which may account for the proinflammatory effect in the P. gingivalis-induced periodontitis murine model." (PMID 33679805, 2021).
periodontitis (continued). "IL-18 may have a significant role in the progress of chronic periodontitis." (PMID 33327639, 2020). "Serum IL-18 levels were associated with HbA1C but not periodontitis." (PMID 32053656, 2020). "Large inter-individual variations in the cytokine responses were found, leading us to suggest that periodontitis patients secrete more IL-1β and IL-18 when exposed to bacterial H2S compared to healthy individuals, which may indicate a higher susceptibility to developing periodontitis." (PMID 31164964, 2019). "Therefore, we hypothesize that there was an association between the polymorphisms in the IL12B, IL18, and MMP9 regions and the development of periodontitis." (PMID 31065235, 2019). "In the first part of the study, we examined the effect of adiponectin on the expression in periodontal ligament cells of mRNA of mediators involved in periodontitis pathogenesis (TNF-α, IL-1, IL-6, IL-8, IL-10, IL-17, IL-18)." (PMID 40282186, 2025). "Several pro-inflammatory cytokines, including IL-1, IL-6, IL-12, IL-17, IL-18, IL-21, TNF-α, and IFN-γ, play a critical role in the pathogenesis of periodontitis." (PMID 40136726, 2025). "As the results of immunohistochemistry showed, the pyroptosis-related protein levels of N-GSDMD, IL-1β, and IL-18, as well as the inflammatory factor TNF-α were significantly augmented in human periodontitis tissues compared with those in the healthy tissues." (PMID 40000642, 2025). "In a recent study, patients with chronic hepatitis C and periodontitis were found with significantly more elevated levels of NLRP3, caspase-1, and IL-18 in GCF samples, than systemic healthy patients with periodontitis." (PMID 38817019, 2024). "The results revealed that the expression of NLRP3, IL‐1β, IL‐18, IL‐6, and TNF‐α was upregulated by F. nucleatum and its OMVs in rats with periodontitis." (PMID 39475060, 2024). "The ROC curves indicated a high accuracy of salivary IL-1β, IL-18, and GSDMD levels as biomarkers of periodontitis and CHD, with an AUC of 1.0 for groups P, AS-C, and AS-P (P < 0.0001)." (PMID 39071510, 2024). "The findings of this study indicate that there is a significant positive correlation between salivary IL-1β, IL-18, and GSDMD levels and clinical periodontal parameters in patients with periodontitis, as well as LDL levels in patients with ASCHD." (PMID 39071510, 2024). "Due to the small sample sizes and the unclear sources of IL-18 secretion in these studies, the potential of NKB cells as a therapeutic regimen for periodontitis remains to be established." (PMID 36405684, 2022). "IL-18, which involves in MSU-induced sterile inflammation, can exaggerate inflammatory responses in periodontitis when released by Natural Killer-Like B cells." (PMID 36466813, 2022). "There was a positive correlation between IL-18 concentration in GCFs and CAL in the maintenance phase of periodontitis." (PMID 33679805, 2021). "It has also been suggested to be involved in periodontal inflammation since elevated IL-18 levels in gingival crevicular fluid (GCF) and saliva were found in patients with chronic periodontitis." (PMID 32053656, 2020). "Immune-inflammatory agents, namely CRP, TNF-α, CXCL10, IL-6, IL-18, sVCAM-1, sICAM-1, IP-10 and MCP-1, have been found in high concentrations in the circulating blood of pregnant individuals diagnosed with preeclampsia who also have periodontitis." (PMID 41394354, 2025). "IL-15 and IL-18 levels were higher in a group of non-smokers with periodontitis than in non-smokers without periodontitis." (PMID 39727461, 2024). "In a murine model of chronic periodontitis induced by P. gingivalis and in acute periodontitis patients, NKB cells were elevated and induced inflammation through secretion of IL-18 and the neutralization of IL-18 prevented bone resorption and inflammation." (PMID 38739675, 2024). "Similarly, elevated IL-18 levels in saliva (Özçaka, Nalbantsoy & Buduneli, 2011) and GCF of periodontitis patients were observed." (PMID 38756445, 2024).
periodontitis (continued). "Another point of our study was to examine IL-18 expression in gingival tissue and to correlate IL-18 expression in gingival tissue with clinical parameters in patients with and without periodontitis." (PMID 36289627, 2022). "Similar to salivary IL-18, serum IL-18 levels were not significantly different between the DM group and the control group or between those with and without periodontitis." (PMID 32053656, 2020). "Human data on serum and salivary IL-17A and IL-18 in patients with DM with and without periodontitis are, however, still sparse." (PMID 32053656, 2020). "Indirectly, these cells can also induce the amplification of the pro-inflammatory cytokines (IL-1, IL-6, IL-12, IL-17, IL-18, IL-21, TNF-α, and IFN-γ), which are known to be found in periodontitis and to induce osteoclastogenesis via the RANKL–RANK–OPG pathway." (PMID 33143068, 2020). "To date, the SNP IL-18 −140 C/G (rs360721) has not been studied in the context of periodontitis yet." (PMID 32630798, 2020). "IL-12 and IL-18/IL-10 ratio was not correlated with periodontitis group." (PMID 39080003, 2024). "It must be considered that despite our results, we cannot preclude that the concentrations of IL-18 and sE-selectin in the GCF of psoriatic patients may be modified to some extent by the presence of periodontitis, as the disease usually modifies the local composition of the GCF." (PMID 34685372, 2021). "However, we only found IL-18, but not IL-12, was elevated in peripheral blood and GCFs of periodontitis patients." (PMID 33679805, 2021). "However, the absence of a group with IBD and without periodontitis enables more comparisons as higher levels of IL-18 have been previously found in the plasma of patients with IBD, especially in CD." (PMID 34501547, 2021). "Moreover, salivary IL-18 levels were not significantly different between those with and without periodontitis." (PMID 32053656, 2020). "Thus, the objective of this study was to evaluate the concentrations of salivary-17A, interleukin-1 beta, and interleukin-18 in patients with celiac disease who are on a gluten-free diet, both with and without periodontitis, and to compare these levels with those in healthy individuals." (PMID 38756445, 2024). "Distinct and independent processes in NLRP3 inflammasomes in vitro are shown to elicit IL-1B and IL-18 production in response to non-canonical stimulation, which can fine-tune the pyroptosis response and is likely to account for the opposing patterns observed in periodontitis samples." (PMID 35844512, 2022). "However, IL-18 also enhances Th2 responses and the synthesis of other pro-inflammatory cytokines, such as TNF, IL-1β, and IL-8, as well as granulocyte colony-stimulating factor and macrophage colony-stimulating factor, which are involved in inflammatory process in periodontitis." (PMID 36289627, 2022). "Furthermore, no increased levels of serum IL-18 in the chronic periodontitis group was revealed." (PMID 32053656, 2020). "Moreover, the researchers observed that IL-18 can initiate NF-κB signalling to promote the release of matrix metalloproteinases: MMP1, MMP2, MMP3 and MMP9, which may have a role in inducing the progression of chronic periodontitis." (PMID 33327639, 2020). "As a result, the study’s aim was to investigate the levels of salivary IL-17A, IL-18, and IL-1B in celiac disease patients on GFD with and without periodontitis compared to healthy controls." (PMID 38756445, 2024). "CD3-CD19+NKp46+ NKB periodontium cells were found to be the major source of IL-18 production in both the serum and the gingival crevicular fluid (GSF) of periodontitis patients; this was not the case in healthy individuals." (PMID 36405684, 2022). "Both groups of periodontitis patients (CHC + P and P) expressed significantly elevated levels for all of the three assessed proinflammatory mediators (NLRP3, CASP1, and IL-18) as compared to the nonperiodontitis groups (CHC and H)." (PMID 34840527, 2021).
periodontitis (continued). "This study found that groups P, AS-C, and AS-P exhibited significantly higher levels of IL-1ß, IL-18, and GSDMD than group C. Furthermore, all the biomarkers showed high accuracy in differentiating patients with periodontitis with and without ASCHD from healthy individuals." (PMID 39071510, 2024).
Hyperglycemia (63 papers, 2010 to 2026). An increased concentration of glucose in the blood. "Therefore, PD exacerbates hyperglycemia by promoting the pathogenic expansion of B cells and their crosstalk with macrophages via the IL-18 signaling axis." (PMID 41858253, 2026). "In addition, short-term acute hyperglycemia caused by refined carbohydrate intake increased circulating levels of free radicals and proinflammatory cytokines such as interleukin (IL)-6, IL-18, and tumor necrosis factor-alpha." (PMID 31167515, 2019). "Hyperglycemia causes release of proinflammatory cytokines (IL-6, IL-8, IL-18, and TNF-α), diminished bioavailability of nitric oxide with attendant endothelial dysfunction, and increased production of oxygen-derived free radicals with enhanced oxidative stress." (PMID 26273664, 2015). "In other studies, but not in accordance with the current findings, increases during hypoglycemia has also been described for TNF-α, Il-8 and VEGF-A, while TNF-α and IL-18 have been demonstrated to increase during hyperglycemia." (PMID 37400734, 2023). "Similar hyperphagia was observed in mice deficient in IL-18R and in mice overexpressing IL-18BP, while central administration of recombinant IL-18 (rIL-18) inhibited food intake and reversed hyperglycemia in IL-18-/- mice." (PMID 36313762, 2022). "Of greater relevance, higher plasma IL-18 levels have been detected in response to acute hyperglycemia in healthy volunteers and subjects with impaired glucose tolerance, suggesting a direct link between IL-18 and elevated glucose levels." (PMID 36499008, 2022). "Proinflammatory cytokines IL-1β, IL-6, IL-18, and TNFα which play major roles in the development and progression of DN are triggered by hyperglycemia and oxidative stress." (PMID 33562428, 2021). "The intracerebral administration of recombinant IL-18 inhibited food intake and reversed hyperglycemia, indicating the tissue-specific function of IL-18 in AT and in the brain." (PMID 33671547, 2021). "Patients presented with hyperglycemia were more likely to have higher levels of IL-6, IL-18 and hs-CRP compared to the normoglycemic patients." (PMID 34117510, 2021). "Hyperglycemia leads to increased inflammatory cytokines of renal tubular epithelial cells and these inflammatory cytokines, such as IL-1, IL-6, IL-18, and TNF-α can directly damage renal tubular cells." (PMID 32073611, 2020). "Not only hyperglycemia but also albuminuria stimulates IL-18 expression in proximal tubular cells which is correlated with our results." (PMID 27703550, 2016). "Hyperglycemia induced by glucose clamping in normal subjects showed a significant increase in the circulating levels of interleukin- (IL-) 6, IL-18, Il-1β, and tumor necrosis factor-α (TNF-α)." (PMID 27034691, 2016). "Consistently, in cultured cardiomyocytes incubated with 30 mmol/l or 50 mmol/l glucose (HG) to mimic hyperglycemia, IL-1β and IL-18 levels were also found significantly increased, indicating an induction of cardiomyocyte pyroptosis." (PMID 25341033, 2014). "Hyperglycaemia has been shown to increase IL-18 expression in adipocytes." (PMID 39064738, 2024). "Hyperglycemia leads to increased inflammasome activity, upregulated nucleotide-binding oligomerization domain-like receptor 3, and ultimately elevated pro-inflammatory interleukin1β and interleukin 18 levels." (PMID 38476673, 2024). "In fact, it has been reported that pro-inflammatory cytokines (e.g., TNFα, interleukin 1β (IL-1β), interleukin 18 (IL-18) and IL-6) are increased in acute hyperglycemia, whereas in the opposite condition, when insulin is working, these cytokines are significantly decreased." (PMID 38137918, 2023). "Interestingly, both TNF-α and IL-6 have been shown to increase similarly during experimental hyperglycemia along with rises in IL-18 and FGF-21 and suppression of VEGF." (PMID 37400734, 2023).
Hyperglycemia (continued). "NF-κB in the renal cortex and NF-κB, IL-18 and Caspase-1 in the renal medulla of the model + LPS group were apparently upregulated, indicating that LPS can promote inflammatory factors by the transcription factor NF-κB in the hyperglycemia model." (PMID 37467292, 2023). "IL-18 may attenuate lipid metabolism, postprandial hyperglycemia, and modulate insulin signalling and by triggering endothelial inflammation, promote the formation of atherosclerotic plaques." (PMID 35160217, 2022). "Moreover, according to the cytokine kit analysis, the VEGF, TNF-α, IL-18 and IL-1β levels in rat plasma demonstrated similar trends, which also supported that H3 relaxin lessened the inflammatory activity induced by hyperglycemia." (PMID 33584279, 2020). "Interestingly, experimental hyperglycemia has been shown to increase the expression of IL-18 in adipocytes, an effect which was even more pronounced in the presence of intermittent hyperglycemia." (PMID 20331890, 2010). "Moreover, according to the WB analysis, the NLRP3, P2X7, IL-18, and IL-1β protein levels in the retinas of mice in the treatment groups demonstrated similar trends, indicating that 3TC reduced the inflammatory activity induced by hyperglycemia." (PMID 35410316, 2022). "One further possible outcome of hyperglycemia could involve the cytokine IL-18." (PMID 25625430, 2015). "Hyperglycemia induces the assembly and activation of the NLRP3 inflammasome, prompting the release of numerous inflammatory factors, such as IL-1β and IL-18." (PMID 41394140, 2025). "The priming phase, triggered by hyperglycemia, oxidative stress, and lipotoxicity, activates NF-κB signaling, leading to increased NLRP3 expression and the production of pro-IL-1β and pro-IL-18." (PMID 40427455, 2025). "Circulating levels of proinflammatory cytokines such as interleukin (IL)−6, IL-18, and tumor necrosing factor-α (TNF-α) are revealed to be elevated by acute hyperglycemia-induced oxidative stress." (PMID 39812937, 2025). "Hyperglycemia, hyperlipidemia, and hyperuricemia trigger the NLRP3 inflammasome, linking metabolic stress in DN to pro-inflammatory responses via IL–1β and IL–18." (PMID 38890983, 2024). "In all participants, hyperglycemia led to significant reductions of 62/70 inflammatory markers across all subcategories including TNF-α, IL-8, IL-18 and VEGF-A." (PMID 37400734, 2023). "Nevertheless, proinflammatory cytokine IL-18 was reported to be elevated in newly diagnosed T2DM and prediabetic patients, and acute hyperglycemia was shown to induce the increase in plasma IL-6, TNF-α, and IL-18 concentrations." (PMID 36547931, 2022). "Hyperglycemia can trigger NLRP3 overactivation and promote the production of cleaved caspase-1, thus accelerating the maturation and release of IL-1β and IL-18, which induce pyroptosis and finally lead to cardiac dysfunction and heart failure." (PMID 35096293, 2021). "Hyperglycemia is also shown to stimulate the expression of NLRP3, resulting in increased secretion of cytokines IL-1β and IL-18." (PMID 31281401, 2019). "In conclusion, hyperglycemia and hyperlipidemia can lead to the activation of NLRP3 inflammasomes, and their downstream molecules, including caspase-1, IL-1β, and IL-18, in the glomerular mesangium." (PMID 28708885, 2017). "Hyperglycemia can also increase the production of reactive oxygen species (ROS), providing the second signal, called the activation signal, as well as initiating NLRP3 complex assembly and active IL-18 and IL-1β production." (PMID 37238986, 2023). "Naringin reduces hyperglycemia, inhibits the proliferation of cells induced by high glucose, and decreases the expression of inflammatory that is mediated by NLRP3 through the NLRP3-caspase-1-IL-1β/IL-18 signaling pathway." (PMID 34371645, 2021).